TIMP1 (TIMP metallopeptidase inhibitor 1)
Diseases named in the same sentence as TIMP1 in open-access papers (continued):
Sharing a sentence is not in itself a finding about the gene and the disease.
lung carcinoma (continued). "Collectively, the present data suggest a pivotal role of cisplatin-induced TIMP-1 release from lung cancer cells in tumor-to-endothelial cell communication resulting in a reduced cancer-associated angiogenic impact on endothelial cells." (PMID 30344920, 2018). "Thirdly, blockade of the cisplatin-induced TIMP-1 release by inhibitors of MAPK signalling pathways likewise conferred a reversal of the inhibitory impact of CM from cisplatin-treated lung cancer cells." (PMID 30344920, 2018). "Subsequent downregulation of miR-210-targeted proteins results in increased pro-angiogenic properties of exosomes released by TIMP-1-overexpressing cells and thus contributes to a new mode of action by which TIMP-1 can support lung cancer progression." (PMID 30309355, 2018). "Since miR-125a-5p showed a significant up-regulation with TIMP-1 knockdown and since it has previously been reported to be both pro-apoptotic and down-regulated in lung cancer, we focused our further studies to miR-125a-5p." (PMID 29507665, 2018). "In the present study we have sought to identify the epigenetic role of miR-125a-5p in the pleiotropic functions of TIMP-1 in lung cancer." (PMID 29507665, 2018). "Tissue inhibitor of metalloproteinases (TIMP)-1 is a factor that strongly supports lung cancer progression and its expression is elevated in all stages and types of lung cancer particularly in adenocarcinoma." (PMID 29720982, 2018). "Here, we provide first-time proof for cisplatin-induced TIMP-1 release from lung cancer cell lines to inhibit angiogenic capacities of endothelial cells." (PMID 30344920, 2018). "We examined Rab37, TIMP1 and PKCα expression patterns in tumor specimens from 158 lung cancer patients and assigned protein expression levels into preserved, overexpressed and low expression by immunohistochemical analysis." (PMID 29312551, 2017). "We previously identified a novel Rab small GTPase protein, Rab37, which plays a critical role in regulating exocytosis of secreted glycoproteins, tissue inhibitor of metalloproteinases 1 (TIMP1) to suppress lung cancer metastasis." (PMID 29312551, 2017). "From a clinical point of view, we identified a group of lung cancer patients with a profile of high PKCα, high Rab37 and low TIMP1 secretion, and this group of patients displayed poor prognosis." (PMID 29312551, 2017). "In the species or tissue-derived cellular microenvironment (for example, PDAC in this study and lung cancer), such protein interactions help to explain the diversity and occasional divergent biology of TIMP-1." (PMID 28030805, 2017). "Lung cancer patients with preserved Rab37, low TIMP1, and high PKCα expression profile correlate with worse progression-free survival examined by Kaplan-Meier survival, suggesting that PKCα overexpression leads to dysfunction of Rab37." (PMID 29312551, 2017). "Based on the detected elevation of endocannabinoids and endocannabinoid-like substances in FAAH inhibitor-treated lung cancer cells, a potential anti-invasive and TIMP-1-upregulating effect of exogenously added AEA, 2-AG, OEA and PEA was investigated next." (PMID 26930716, 2016). "Of note, reconstituted TIMP1 by addition of TIMP1 recombinant protein abolishes the migration and invasion ability of lung cancer cells in vitro and in vivo." (PMID 27716280, 2016). "An 8-marker model was developed (TFPI, MDK, OPN, MMP2, TIMP1, CEA, CYFRA 21–1, SCC) which accurately distinguished subjects with lung cancer (n = 50) from high risk smokers (n = 50) in an independent validation study (AUC = 0.775)." (PMID 26279647, 2015). "The present study was undertaken to elucidate the role of TIMP-1 in the context of apoptosis, using the same lung cancer cell lines." (PMID 26366732, 2015). "A carefully done study of 63 patients who had surgery for lung cancer or lung transplantation demonstrated that increasing TIMP-1 and MMP-2 mRNA in the small airways and/or the parenchyma surrounding the small airway was positively associated with FEV1." (PMID 24447332, 2014).
lung carcinoma (continued). "Jee and colleagues demonstrated that KAI1/CD82 upregulated TIMP-1 to suppress tumor cell invasion in lung carcinoma model." (PMID 23840773, 2013). "Even though Ramer’s work demostrated CBD-driven TIMP-1 upregulation and consequent decrease of invasion in cervical and lung cancer cells, this discrepancy is likely due to the different kind of tumor considered." (PMID 24204703, 2013). "All groups had similar expression levels for most of the proteins analysed except TIMP-1 which was higher in the lung cancer resection, MMP-2 which was higher in lung transplant biopsy and VEGFA, which was elevated in pneumothorax samples." (PMID 22593690, 2012). "Despite the high gene expression levels of VEGFA, PGF, FLT1, KDR, MMP-2, TIMP-1, and TIMP-2, only KDR and TIMP-1 were high at the protein level in the lung cancer resections." (PMID 22593690, 2012). "Moreover, phosphorylation on threonine 172 (T172) negatively regulates Rab37 activity, and impairs the Rab37-induced exocytosis of TIMP1, resulting in the suppression activity of Rab37 on lung cancer cell motility." (PMID 38695990, 2024). "We already confirmed that either high glucose or serum starvation could activate Rab37 and induce secretory autophagy to promote exocytosis of insulin from β‐cell and TIMP1 from lung cancer cells." (PMID 38804615, 2024). "By contrast, dysfunction of Rab37 or TIMP1 abolishes metastatic suppression of lung cancer cells." (PMID 38695990, 2024). "Using single‐cell RNA‐Seq data from human primary lung cancers, we found that the highest expression of TIMP1 occurs in fibroblasts, endothelial cells, monocytes and pericytes matching the immunohistochemistry staining pattern that we found in both human and mice lung tumours." (PMID 37759102, 2023). "Interestingly, another study showed that MAGL inhibition can exert antiangiogenic effect by inducing the release of tissue inhibitor of metalloproteinase-1 (TIMP-1) from lung cancer cells." (PMID 38004429, 2023). "Furthermore, we used a recently published dataset of lung cancer that contains overall survival and proteomics of the tumours and found that higher protein levels of TIMP1 correlate with unfavorable prognosis." (PMID 37759102, 2023). "In another recent study, parameters of endothelial angiogenesis were reduced by conditioned media (CM) of lung cancer cells previously treated with MAGL inhibitors, clarifying TIMP-1 (tissue inhibitor of metalloproteinases-1) induction in cancer cells as the underlying mechanism." (PMID 37830546, 2023). "Furthermore, CBD increases the expression of TIMP-1 and decreases the expression of PAΙ-I, thereby reducing the invasiveness and metastatic potential of lung cancer cells." (PMID 36437760, 2022). "As TIMP-1 upregulation is prevented by ICAM-1 neutralizing antibodies or silencing microRNA, the authors concluded that the cellular adhesion and signaling molecule ICAM-1 are implicated in the beneficial effects of cannabinoid compounds on lung cancer." (PMID 36437760, 2022). "Therefore, JWH133 increased TIMP-1 production in lung cancer cells and induced ICAM-1 expression, thereby modifying the tumor cell microenvironment and inhibiting angiogenesis." (PMID 34393784, 2021). "Moreover, the study finds that levels of mature miR-210 was dependent on CD63, an interacting partner of TIMP-1, providing novel insight into the mechanism of elevated miR-210 in lung cancer." (PMID 34440422, 2021).
lung carcinoma (continued). "Obtained results clearly demonstrate the importance of mentioned regulators for LUAD/LUSC progression: it was shown that up-regulation of PTX3, TIMP1, SERPINE1, and PLAUR not only on mRNA, but also on protein level was significantly associated with poor survival in patients with lung cancers." (PMID 34807957, 2021). "The upregulation of ICAM-1 and TIMP-1 then attenuates the invasion of lung cancers." (PMID 33143283, 2020). "The difference in TIMP-1 expression between A549 and H1703 cells under the same microgravity conditions demonstrates that these cells have different migration and metastasis potentials, even in the same lung cancers." (PMID 31601869, 2019). "Besides this antiproliferative action, AEA was further shown to inhibit lung cancer cell invasion and metastasis via upregulation of tissue inhibitor of matrix metalloproteinases-1 (TIMP-1) and to induce apoptosis in human gastric adenocarcinoma." (PMID 31143113, 2019). "Relevant to this study, it has been reported that TIMP-1 could be induced by PT and partially mediates the anti-angiogenic and anti-invasive roles of the drug in lung cancer cells models." (PMID 31861382, 2019). "TIMP-1 and -2 have been shown to participate in pulmonary diseases characterized by alterations of the alveolar structure or abnormal remodeling responses such as emphysema, interstitial fibrosis, acute respiratory distress syndrome, and lung cancer." (PMID 30781876, 2019). "It has been recently reported that the CM from lung cancer cells treated with cisplatin slightly increased the proliferation and decreased the tube formation activity and motility of endothelial cells via the regulation of TIMP-1." (PMID 31861382, 2019). "We also show that Rab37 is phosphorylated by protein kinase Cα (PKCα) at threonine 172 (T172), leading to attenuation of its GTP-bound state, and impairment of the Rab37-mediated exocytosis of TIMP1, and thus reduces its suppression activity on lung cancer cell motility." (PMID 29312551, 2017). "Nicol and coworkers used an immunoaffinity approach to quantify carincoembryonic antigen (CEA), secretory leukocyte peptidase inhibitor, tissue factor pathway inhibitor 1,2 (TFPI/TFPI2), and metalloproteinase inhibitor 1 (TIMP1) in sera samples from lung cancer patients down to low ng/ml levels." (PMID 26097198, 2015). "TIMP-1 was higher at both the transcriptional and protein levels in the lung cancer specimens." (PMID 22593690, 2012). "Notably, Rab37 activation has been reported to direct vesicle trafficking toward the extracellular secretion of tissue inhibitor of metalloproteinase 1 (TIMP1) in lung cancer cells under starvation, as well as for insulin secretion, likely through increased MAP1LC3/LC3." (PMID 40422252, 2025). "Despite these limitations, we showed that TIMP1 is a sensitive biomarker for lung cancer in mice and humans and we believe that the data presented in this manuscript could have broad implications for early diagnosis, follow up, and stratification of lung cancer patients." (PMID 37759102, 2023). "Thus, we conclude that TIMP1 is an agnostic biomarker for lung cancer." (PMID 37759102, 2023). "Together, these data suggest that TIMP1 is produced by the tumour and surrounding stromal cells in a pro‐inflammatory milieu, and its concentration in plasma could be used as a biomarker for lung cancer detection." (PMID 37759102, 2023). "Therefore, the motility suppression of lung cancer cells by Smp24 may be associated with its changes of mRNA levels of MMP-2/-9 and TIMP-1/-2 plus F-actin reorganization." (PMID 35878176, 2022). "Moreover, meta-analysis of clinical data from publicly available databases (TCGA database) of LUAD in this study supports TIMP-1 being an important potential biomarker in lung cancer, as significantly elevated levels of TIMP-1 are seen in NSCLC tissues in comparison to benign lung tissue." (PMID 31443242, 2019).
lung carcinoma (continued). "Whether Sp1 or miR-182 regulates TIMP-1 in lung cancer needs to be addressed in future studies." (PMID 24519909, 2014). "MMP-9/TIMP-1 imbalance is a common mechanism of malignant tumor invasion and metastasis, and PI3K/AKT/NF-κB pathway plays a key role in the process of lung cancer metastasis." (PMID 36690987, 2023). "CBD was found to increase TIMP-1 and ICAM-1 expression in a dose-dependent manner in lung cancer cell lines and inhibited the spread and invasion of human lung cancer xenografts in mice, partially due to the increase in ICAM-1 and TIMP-1." (PMID 37397476, 2023). "The currently available literature indicates that exosomal miR-210 is involved in the regulation of various lung cancer-related signaling molecules and pathways, including STAT3, TIMP-1, KRAS/BACH2/GATA-3/RIP3, and PI3K/AKT." (PMID 34440422, 2021). "In lung cancer, both AA-5HT and URB597 contrast tumor invasion through TIMP-1 upregulation, likely in a CB2- and TRPV1-dependent way." (PMID 31979368, 2020). "In lung cancer, silencing of NFIX induced a decrease in IL6ST, TIMP1, and ITGB1 gene expression and reduced cell proliferation, migration, and invasion processes." (PMID 31766658, 2019). "URB597 and AA-5HT were further found to decrease human lung cancer cell invasion via CB2- and TRPV1-dependent upregulation of TIMP-1." (PMID 31143113, 2019). "Similar results of inhibitory effects of PKCα-mediated T172 phosphorylation of Rab37 on cellular distribution, Rab37-mediated TIMP1 and TSP1 secretion and motility suppression were observed in another lung cancer cell line A549." (PMID 29312551, 2017). "The gene expression level of VEGFA, PGF, and their receptors FLT1 and KDR as well as MMP-2 and the inhibitors TIMP-1 and TIMP-2 was higher in samples from lung cancer resections compared to pneumothorax and transplant biopsy samples." (PMID 22593690, 2012). "Lung cancer resections had higher expression levels of TIMP-1 compared to pneumothorax and transplant biopsies while the level of KDR was higher in both the lung cancer and transplant biopsies." (PMID 22593690, 2012). "Immunohistochemical studies showed lower expression levels of VEGFA and MMP-2 in lung cancer resections compared to pneumothorax and transplant biopsies, while in contrast TIMP-1 and KDR expression was higher in lung cancer." (PMID 22593690, 2012). "Gupta further revealed that lung adenocarcinoma cells produce TIMP-1 and TIMP-2, whereas lung SCC cells only express TIMP-2, suggesting that MMP and TIMP differential expression, mediated by the CCR9/CCL25 axis, influences lung cancer metastasis and invasion." (PMID 40607416, 2025). "First, our clinical samples consisted only of subjects with NSCLC and we did not evaluate the relationship of TIMP1 to other lung cancer types." (PMID 37759102, 2023). "Using two different cell lines for lung cancer, it was shown that NFIX regulates interleukin-6 receptor subunit β (IL6ST), metalloproteinase inhibitor 1 (TIMP1), and integrin β-1 (ITGB1) genes, all of which are involved in cell proliferation, migration, and invasion." (PMID 36901722, 2023). "A further indirect effect, here mediated by cannabinoid-induced increased formation of anti-angiogenic TIMP-1, was reported for the effect of conditioned media from CBD-, THC-, Met-AEA- and JWH-133-treated lung cancer cells on tube and sprout formation and endothelial cell migration." (PMID 35277658, 2022). "Furthermore, we analyzed the correlation of the expression of hub gene in lung cancer tissues, of which PECAM1, VWF, CD34, COL1A1, MMP9 and TIMP1 are closely related." (PMID 33850663, 2021). "A study comparing gene expression in lung tissues by microarray analysis from five patients with both lung cancer and IPF revealed five genes e.g. SMAD4, P21, MT1A, MMP7 and TIMP1; these were down-regulated in cancer tissue in comparison to IPF, in at least two of the patients." (PMID 33905434, 2021).
lung carcinoma (continued). "Overlapping these gene sets revealed that 4 genes (PTX3, TIMP1, SERPINE1, and PLAUR) are common to both LUSC and LUAD patients, which may indicate the universality of these markers for the occurrence of lung malignant neoplasms." (PMID 34807957, 2021). "Therefore, it is necessary to carefully observe changes in TIMP-1 levels in addition to MMP-2 and MMP-9 to analyze lung cancer migration in the microgravity environment." (PMID 31601869, 2019). "HUVECs were exposed to CM obtained from lung cancer cells that were treated with vehicle or 1 μM cisplatin in the presence or absence of TIMP-1 siRNA or a non-silencing siRNA control." (PMID 30344920, 2018). "TIMP1 was shown to play a role in cell survival independently of its inhibitory function to MMPs via specific cellular signaling pathways such as the ERK and AKT pathways in various cell types (e.g., breast epithelial cells and lung cancer cells)." (PMID 29742163, 2018). "In lung cancer, CBD inhibits invasion of A549 cells both in vitro and in vivo that was accompanied by up-regulation of tissue inhibitor of matrix metalloproteinase-1 (TIMP-1) and decreased expression of plasminogen activator inhibitor-1 (PAI-1)." (PMID 25115386, 2014). "The gene expression level of VEGFA, PGF, and their receptors FLT1 and KDR as well as MMP-2 and the inhibitors TIMP-1 and TIMP-2 was significantly higher in lung cancer specimens compared to pneumothorax samples and biopsies from lung transplant patients (P < 0.001)." (PMID 22593690, 2012). "In another recent study performed on normoxic lung cancer cells, angiogenic parameters of HUVECs were reduced by CM of lung cancer cells previously incubated with MAGL inhibitors, with the release of antiangiogenic TIMP-1 playing a critical role in this process." (PMID 37830546, 2023). "Finally, considering the identified association of ALI-specific key genes with poor prognosis in LUAD/LUSC patients, TIMP1, SERPINE1, PLAUR, and PTX3 may be used as marker genes to control the severity of lung cancer progression in the case of accompanying pulmonary inflammation." (PMID 34807957, 2021). "It has been shown that the increase in TIMP-1 levels may upregulate miR-210 by induction of pro-tumorigenic PI3K/AKT/HIF-1 signaling pathway, whereas EVs released by TIMP-1 overexpressing cells may exhibit significantly increased pro-angiogenic activities during lung cancer progression." (PMID 30322133, 2018). "Hence, NFIX with IL6ST, TIMP1, ITGB1, PTCH1, GGCX and NFAT5 genes may regulate the migration and invasion process and they could serve as potential therapeutic targets in patients with lung cancer to predict survival and improve prognosis." (PMID 28871224, 2017). "Interestingly, in our lung carcinoma model, we have shown that BAD is phosphorylated at Ser-112 and not at Ser-136, thereby confirming our findings that TIMP-1 activated cell survival does not involve Akt activation." (PMID 26366732, 2015).